LRRFIP2 (LRR binding FLII interacting protein 2)
Description:
May function as activator of the canonical Wnt signaling pathway, in association with DVL3, upstream of CTNNB1/beta-catenin. Positively regulates Toll-like receptor (TLR) signaling in response to agonist probably by competing with the negative FLII regulator for MYD88-binding.
Synonyms: HUFI-2
Tractability: Antibody: the Human Protein Atlas places it where antibodies can reach. PROTAC: ubiquitination databases record sites on it; its protein half-life has been measured.
Gene: Protein-coding gene on chromosome 3 (37,052,626 to 37,183,689, reverse strand). Ensembl gene ENSG00000093167.
Subcellular location (Human Protein Atlas): Actin filaments; Plasma membrane
Gene Ontology:
Molecular function: LRR domain binding; protein binding
Biological process: regulation of DNA-templated transcription
Genetic constraint (gnomAD): Loss-of-function variants: 61 observed, 65.97 expected, observed/expected ratio (o/e) 0.92, 90% interval 0.75 to 1.14. The upper end of that interval is the gene's LOEUF score, 1.14, which puts it in group 5 of 6, group 1 being the genes least tolerant of losing a copy. Missense variants: 548 observed, 575.09 expected, observed/expected ratio (o/e) 0.95, 90% interval 0.89 to 1.02. Synonymous variants: 195 observed, 199.87 expected, observed/expected ratio (o/e) 0.98, 90% interval 0.87 to 1.1.
Homologues: Orthologues: chimpanzee LRRFIP2 (99% identical), macaque LRRFIP2 (98% identical), dog LRRFIP2 (92% identical), pig LRRFIP2 (92% identical), guinea pig LRRFIP2 (91% identical), mouse Lrrfip2 (90% identical), rat Lrrfip2 (90% identical), rabbit LRRFIP2 (80% identical), tropical clawed frog lrrfip2 (68% identical), zebrafish lrrfip2 (44% identical), Drosophila melanogaster CG8578 (23% identical), Caenorhabditis elegans flap-1 (17% identical). Paralogues in human: LRRFIP1 (47% identical).
Diseases named in the same sentence as LRRFIP2 in open-access papers:
LRRFIP2 is named in the same sentence as 19 diseases in open-access papers, as found by Europe PMC text mining. Sharing a sentence is not in itself a finding about the gene and the disease. The quoted sentences say what the papers report.
gastric cancer (6 papers, 2022 to 2025). A primary or metastatic malignant neoplasm involving the stomach. "To address the functional significance of the association of LRRFIP2 variant 3 expression with clinical outcomes in gastric cancers, we performed Kaplan-Meier survival using gene expression profiles and clinical data from stage IV gastric cancer patients." (PMID 36307405, 2022). "Collectively, these in vitro and in vivo data suggest that the presence of exon 7 in LRRFIP2 variant 3 greatly increases the metastatic potential of gastric cancer cells." (PMID 36307405, 2022). "Overexpression of LRRFIP2 variant 3 contributed to the metastasis of gastric cancer cells by modulating the histone methylation activity of coactivator-associated arginine methyltransferase 1 (CARM1)." (PMID 36307405, 2022). "Of note, a significantly lower expression level of ESRP1 and a higher expression level of LRRFIP2 variant 3 were observed in more advanced gastric cancer stages." (PMID 36307405, 2022). "To further investigate whether the presence of exon 7 of LRRFIP2 variant 3 is indeed important for dramatic changes in metastatic potential in gastric cancer cells, we deleted exon 7 of endogenous LRRFIP2 variant 3 using the CRISPR/Cas9 system." (PMID 36307405, 2022). "We next examined the effect of ESRP1 regulation on LRRFIP2 variant changes in gastric cancer." (PMID 36307405, 2022). "Notably, gastric cancer patients with higher than twofold upregulated LRRFIP2 variant 3 expression in tumor tissues compared to their matched normal tissues exhibited significantly shorter overall survival times than others." (PMID 36307405, 2022). "Although the possibility that this phenotype is caused by the gain of function of LRRFIP2 variant 2 in addition to the loss of function of variant 3 cannot be ignored, we observed that exon 7 is indeed an important factor determining the metastatic properties of gastric cancer cells." (PMID 36307405, 2022). "LRRFIP2 expression is higher in high ESRP1-expressing cell lines, while LRRFIP variant 3 is higher in low ESRP1-expressing cell lines, determining gastric cancer cell metastasis via differential protein interaction with methyltransferase CARM1." (PMID 40046628, 2025). "By inhibiting CARM1, the invasiveness of LRRFIP2-overexpressing gastric cancer cells can likely be repressed." (PMID 37536629, 2023). "Recently, ESRP1 was reported to regulate the isoform switch of LRRFIP2 and to determine the metastasis of gastric cancer." (PMID 38069324, 2023). "Further, overexpression of a specific leucine-rich repeat (in FLII)-interacting protein 2 (LRRFIP2) splice variant that directly interacts with CARM1 and activates it, also contributes to the metastasis of gastric cancer cells." (PMID 37536629, 2023). "Here, we show that epithelial and mesenchymal isoform switches of leucine-rich repeat Fli-I-interacting protein 2 (LRRFIP2) regulated by epithelial splicing regulatory protein 1 (ESRP1) correlate with metastatic potential of gastric cancer cells." (PMID 36307405, 2022). "Taken together, we report LRRFIP2 as an alternative splicing target of ESRP1 in gastric cancer, which represents a regulatory mechanism of LRRFIP2 splicing variants in gastric cancer metastasis." (PMID 36307405, 2022). "Taken together, our data reveals a mechanism of LRRFIP2 isoform switches in gastric cancer with important implication for cancer metastasis." (PMID 36307405, 2022). "An interrogation of the gastric cancer data sets in TCGA was performed to examine the correlation between the expression of ESRP1 and LRRFIP2 variant 3 in metastatic progression." (PMID 36307405, 2022). "In this study, we demonstrate an alternative splicing target of ESRP1, leucine-rich repeat Fli-1-interacting protein 2 (LRRFIP2), in gastric cancer cells." (PMID 36307405, 2022).
gastric cancer (continued). "Given that the expression of LRRFIP2 variant 3 significantly induced the cell motility and invasiveness of gastric cancer cells, it seemed necessary to verify the functions of the isoforms of LRRFIP2 in regulating metastatic potential." (PMID 36307405, 2022). "Taken together, these results suggest that the relative frequencies of LRRFIP2 isoform switching are highly correlated with the expression levels of ESRP1 in human gastric cancer cell lines and gastric patient tissues." (PMID 36307405, 2022). "In addition, although detailed studies and further validation are needed to assess their clinical significance, we propose that LRRFIP2 variants (2 or 3) may serve as potential biomarkers for gastric cancer liver metastasis and as therapeutic biomarkers for CARM1 inhibitors." (PMID 36307405, 2022). "In this study, based on transcript profiles and isoform switch analysis of 18 gastric cancer cells and 18 gastric patient tissues, we demonstrated the significant association between the expression of ESRP1 and the alternative splicing of LRRFIP2 in gastric cancer cells." (PMID 36307405, 2022). "And ESRP1-induced isoform switching of LRRFIP2 may inhibit metastasis of gastric cancer." (PMID 38114495, 2023). "In gastric cancer, it has been reported that ESRP1 can promote exon 7 splicing of LRRFIP2 and inhibit migration and invasion." (PMID 38114495, 2023). "The frequencies of LRRFIP2 splicing events were directly correlated with the ESRP1 expression level, and the RNA sequencing results from the 18 gastric cancer cell lines and 18 tissue samples were confirmed by RT-PCR." (PMID 36307405, 2022). "In addition to LRRFIP2, other splicing candidates of ESRP1 in gastric cancer cells have been discovered by our RNA sequencing analysis." (PMID 36307405, 2022). "In addition to LRRFIP2, CCDC50, another splicing candidate of ESRP1, also showed skipping exon event and BICD2 showed retained intron event occurring in gastric cancer cells depending on the expression of ESRP1." (PMID 36307405, 2022).
Lynch syndrome (3 papers, 2020 to 2021). An autosomal dominant hereditary neoplastic syndrome characterized by the development of colorectal carcinoma and a high risk of developing endometrial carcinoma, gastric carcinoma, ovarian carcinoma, renal pelvis carcinoma, and small intestinal carcinoma. "LRRFIP2 is associated with an MLH1 mutation that affects the occurrence of Lynch syndrome." (PMID 34778456, 2021). "In another study conducted on a Lynch syndrome family, it was found that the MLH1.ITGA9 fusion allele caused loss of heterozygosity (LOH) in five genes, including LRRFIP2, which resulted in the loss of mismatch repair capabilities." (PMID 32828126, 2020). "LRRFIP2 is associated with hereditary non-polyposis CRC (Lynch Syndrome)." (PMID 33868829, 2021). "In Lynch syndrome, Morak and colleagues discovered a paracentric inversion on chromosome 3p22.2 between the DNA mismatch repair gene MLH1 and the downstream LRRFIP2 gene transcribed in the antisense direction." (PMID 32828126, 2020).
prostate carcinoma (3 papers, 2010 to 2021). A carcinoma that arises from epithelial cells of the prostate gland. "LRRFIP2 splice variants were identified in colon and prostate cancers." (PMID 20967208, 2010). "Another study has shown that LRRFIP2 is involved in the selective cleavage of colon cancer and prostate cancer." (PMID 33854615, 2021). "In this study, LRRFIP2 was identified as a candidate gene for alternative splicing in colon and prostate cancer." (PMID 32828126, 2020).
acral melanoma (1 paper, 2024). "Notably, LRRFIP2 has also been involved in fusions with RAF1 in acral melanoma and with MLH1 in hereditary non-polyposis colorectal cancer." (PMID 39906487, 2024).
Alzheimer disease (1 paper, 2025). A progressive, neurodegenerative disease characterized by loss of function and death of nerve cells in several areas of the brain leading to loss of cognitive function such as memory and language. "Notably, LRRFIP2 has also been implicated in other brain and mental disorders, such as Alzheimer's disease." (PMID 40019038, 2025).
breast carcinoma (1 paper, 2023). "The process was repeated in MCF-7 breast cancer cells, where all but one anticancer gene, LRRFIP2-partial overlap, triggered cell death." (PMID 37864183, 2023).
colorectal cancer (1 paper, 2024). A primary or metastatic malignant neoplasm that affects the colon or rectum. "In this study, we detected an ALK fusion with LRRFIP2 as the 5′partner in a case of colorectal cancer." (PMID 39906487, 2024).
oligodendroglioma (1 paper, 2023). A well-differentiated (WHO grade II), diffusely infiltrating neuroglial tumor, typically located in the cerebral hemispheres. "One of the ATRX-deficient samples with MMR-d (case #17) was a recurrent tumor showing oligodendroglioma-like morphology and harboring fusions involving the NTRK2 and LRRFIP2 genes." (PMID 37891325, 2023).
peritonitis (1 paper, 2013). Inflammation of the peritoneum (tissue that lines the abdominal wall and covers most of the organs in the abdomen). "Given that LRRFIP2 inhibits NLRP3 inflammasome activation in vitro, we further demonstrated the biological effect of LRRFIP2 in vivo by knocking down LRRFIP2 in a mouse peritonitis model." (PMID 23942110, 2013).
schizophrenia (1 paper, 2025). A major psychotic disorder characterized by abnormalities in the perception or expression of reality. "The biological mechanisms involving LRRFIP2 are evident across multiple pathological contexts, suggesting that this gene may influence schizophrenia risk through diverse regulatory pathways." (PMID 40019038, 2025).
cancer (4 papers, 2016 to 2022). A tumor composed of atypical neoplastic, often pleomorphic cells that invade other tissues. "LRRFIP2 may be involved in cancer progression through regulating Wnt signaling pathway." (PMID 33224957, 2020). "Some identified prognostic DE RBPs have not been associated with cancers, such as CELF4, POP1, TDRD6, TDRD7, LRRFIP2, and ZC3H12C." (PMID 33224957, 2020). "LRRFIP2, WDR82 and ACOT1 were not identified previously as possible biomarkers for any type of cancer." (PMID 29285267, 2017). "However, in men, inhibition of STMN1 and LRRFIP2 could not overcome dysregulation of the MAPK and Wnt signaling pathways or aberrant cell cycle and apoptosis regulation, thus resulting in cancer." (PMID 26895224, 2016).
tumor (4 papers, 2022 to 2024). "Next, we evaluated whether overexpression of LRRFIP2 variants 2 and 3 affected cell proliferation and tumor growth." (PMID 36307405, 2022).
infection (1 paper, 2013). The state of being infected such as from the introduction of a foreign agent such as serum, vaccine, antigenic substance or organism. "LvLRRFIP2 was knocked down and the cumulative mortality of L. vannamei upon V. parahaemolyticus, S. aureus, and WSSV infection were detected to further study the function LRRFIP2 in the immune pathway of L. vannamei." (PMID 23468989, 2013).
LRRFIP2 also shares sentences with these, for which no sentence is quoted: colon cancer (2 papers); rectal cancer (2); gastric tumor (1); hereditary non-polyposis colorectal cancer (1); mental disorder (1); rectum tumors (1).